B4GALT1 (beta-1,4-galactosyltransferase 1)
Diseases named in the same sentence as B4GALT1 in open-access papers (continued):
Sharing a sentence is not in itself a finding about the gene and the disease.
tumor (continued). "Our results further demonstrated that B4GALT1 contributed to carcinogenesis via the augmentation of tumour cell proliferation, migration, and invasiveness in LUAD." (PMID 37303063, 2023). "We examined the growth of various strongly or weakly immunogenic tumor cell lines transplanted into B4galt1, B4galt3, and B4galt4 knockout (KO) mice." (PMID 37901252, 2023). "The results confirmed lower B4GALT1 expression in HCC tissue relative to adjacent non-tumor liver tissue." (PMID 37907465, 2023). "The tumour volume in the B4GALT1 knockdown group decreased significantly compared with that in the control group." (PMID 37303063, 2023). "We found that B4galt1 knockdown limited tumour growth compared to the control group, consistent with PD-1 mAb treatment." (PMID 37303063, 2023). "In particular, cotreatment with PD-1 mAb and B4galt1 inhibition led to the most significant enrichment of activated CD8 + T cells in tumour regions." (PMID 37303063, 2023). "In our animal studies, we showed that B4GALT1 inhibition significantly decreased the tumour volume, which was similar to the effect of PD-1 blockade." (PMID 37303063, 2023). "Collectively, these results indicated that B4GALT1 contributed to tumour immune escape by upregulating PD-L1 expression and inhibiting CD8 + T-cell infiltration." (PMID 37303063, 2023). "At the experimental endpoint, the average weight of tumours in the B4GALT1 knockdown group was significantly lower than that in the control group." (PMID 37303063, 2023). "As expected, re-expression of B4GALT1 promoted RBMS1-depleted 4T1 tumor growth in the immune competent model." (PMID 35538152, 2022). "Strictly speaking, the previous study only implanted SiB4GALT1 tumor cells in nude mice, and this was also the first time that the HCC phenotype was studied in B4GALT1-deficient mice." (PMID 35267641, 2022). "Subsequently, highly expressed B4GALT1 can promote PD-L1 glycosylation and increase PD-L1 protein stability, weakening the body’s antitumor immune response and promoting tumor immune escape." (PMID 36568388, 2022). "To explore the expression levels of B4GALT1 in normal and tumor tissues, we analyzed the expression levels of B4GALT1 mRNA in different tumor and normal tissues using the TIMER database." (PMID 36568388, 2022). "Collectively, RBMS1 ablation reduces the level of B4GALT1 to inhibit the glycosylation of PD-L1, thereby stimulating the anti-tumor T-cell immunity." (PMID 35538152, 2022). "Biologically, this complex is essential for in vitro and in vivo tumour growth of CRPC cells after androgen deprivation as it represses B4GALT1, a unique tumour suppressor gene in PCa." (PMID 32902124, 2020). "Collectively, these data suggested that the AR‐V7 target gene B4GALT1, as a novel tumour suppressor in PCa, was negatively regulated by AR‐V7/AKR1C3 complex." (PMID 32902124, 2020). "Biologically, this complex was essential for in vitro and in vivo tumour growth of CRPC cells under ADT by uniquely repressing B4GALT1 expression." (PMID 32902124, 2020). "It will be important in the future to assess the effect of in vivo inhibition of B4GALT1 in LUAD tumor growth either alone or combined with inhibitors of other CSC-enriched targets, such as SCD1." (PMID 31717588, 2019). "Despite the large size of primary tumor and metastasis tissues analyzed, we had the chance to assess the B4GALT1 methylation status in only 49 plasma samples." (PMID 31635093, 2019). "The study population included also two training and two validation sets in order to evaluate the methylation status of B4GALT1 in the primary tumor, metastasis, and plasma specimens of mCRC patients." (PMID 31635093, 2019). "The overall concordance of B4GALT1 methylation between primary tumor tissues and metastasis samples was 62% (23/37 patients)." (PMID 31635093, 2019).
tumor (continued). "Immunohistochemistry was conducted to evaluate B4GALT1 expression in tumor cores, the connection between B4GALT1 expression and patients’ clinical characteristics, and clinical results." (PMID 29793447, 2018). "Univariate Cox regression analysis showed that tumor pT stage (pT4 vs. pT2, HR = 1.765, 95%CI: 1.005~ 3.100, P = 0.049) and B4GALT1 expression (HR = 1.849, 95%CI: 1.126~ 3.035, P = 0.016) were associated with OS in the training cohort." (PMID 29793447, 2018). "Additionally, we will test combination regimens with gemcitabine—given B4GALT1’s role in chemoresistance—and with checkpoint blockade (anti–PD-1/PD-L1), to explore potential synergy in overcoming the immunosuppressive tumor microenvironment typical of PDAC." (PMID 40860122, 2025). "Methylation alterations in the promoter region of B4GALT1 may lead to aberrant gene silencing or overexpression, thereby influencing glycosylation patterns and tumor behavior in HNSCC." (PMID 38562924, 2024). "Besides, slight disparity was discovered in methylation level of B4GALT1 between tumor species and the normal ones." (PMID 38562924, 2024). "For example, proteins involved in the regulation of cell cycle progression, apoptosis, DNA repair, and epithelial-mesenchymal transition (EMT) may cooperate with B4GALT1 to promote tumor growth, invasion, and metastasis." (PMID 38562924, 2024). "At the same time, galectin-8 could then suppress cell migratory activity of B4GALT1-expressing CRC cells to reduce tumor progression." (PMID 39231945, 2024). "Therefore, we compared the expression levels of well-known immune checkpoint molecules between tumours with high and low B4GALT1 expression." (PMID 37303063, 2023). "In addition, B4GALT1 was identified to play a pivotal role in immune evasion to participate in the malignant behaviours of LUAD tumour cells." (PMID 37303063, 2023). "Notably, CD274 (PD-L1) exhibited the most significantly higher expression in B4GALT1-high tumours than in B4GALT1-low tumours." (PMID 37303063, 2023). "We subcutaneously injected A549 cells into BALB/c nude mice to determine whether B4GALT1 influences LUAD tumour growth in vivo." (PMID 37303063, 2023). "We also examined tumor growth in B4galt1 or B4galt4 KO mice." (PMID 37901252, 2023). "Transwell assays also demonstrated that B4GALT1 knockdown impeded tumour migration." (PMID 37303063, 2023). "B4galt1 is a widely studied gene in the B4galt gene family; however, its function in tumor immunity is unknown." (PMID 37901252, 2023). "Moreover, Ki67 staining showed a decrease in the proportion of Ki67-positive cells among tumours formed by B4GALT1 knockdown." (PMID 37303063, 2023). "High expression of B4GALT1 was inversely related to a CTL-mediated survival benefit, implying that in tumour microenvironments characterized by high B4GALT1 expression, CTLs may become dysfunctional." (PMID 37303063, 2023). "We found that B4GALT1 is highly expressed in eight tumor types and low in six tumor types." (PMID 36568388, 2022). "Interestingly, B4GALT1 was also overexpressed, albeith at a lesser level, in reactive pneumocytes located in fibrous remodeled lung parenchyma nearby the tumor." (PMID 36499368, 2022). "Both galectin-3 and B4GALT1 may affect signaling pathways involved in cell–cell communication, in tumor cell dissociation and invasion, in cell-matrix interactions, in tumor angiogenesis, in immune modulation, and in metastasis formation." (PMID 36499368, 2022). "However, when RBMS1 is depleted, it destabilizes B4GALT1 transcript, resulting in the suppression of glycosylation and increased degradation of PD-L1, thus promoting anti-tumor T-cell immunity and sensitizing TNBC cells to anti-CTLA4 therapy." (PMID 35538152, 2022). "B4GALT1 was proposed as a new therapeutic biomarker in this type of tumor." (PMID 36499368, 2022).
tumor (continued). "In this study, based on the analysis of TCGA database, we demonstrated that down‐regulated B4GALT1 in high‐grade, lymph‐node metastatic and biochemical recurrent PCa tissues predicts a poor prognosis of patients, indicating its role as a novel tumour suppressor in PCa." (PMID 32902124, 2020). "Expression analyses using TCGA confirmed tumor downregulation of FAM189A2 and tumor−upregulation of KRT7 and B4GALT1." (PMID 41567189, 2025). "Functionally, B4GALT1 promotes chemoresistance in PDAC via NF-κB-mediated upregulation and stabilization of CDK11^p110 through glycosylation, leading to tumor growth and gemcitabine resistance." (PMID 40860122, 2025). "The results showed that the expression of B4GALT1 and XBP1 was mainly enriched in the tumor region of EC." (PMID 38517922, 2024). "The expression of B4GALT1 and B4GALT4 in paired normal and tumor colon tissues was further examined by IHC." (PMID 39231945, 2024). "The results showed that CLDN9, AK4, PC, GPC1, and SRD5A3 were upregulated in EC tissues compared to in normal endometrium tissues, whereas B4GALT1, GMPPB, B4GALT4, and CHST6 were downregulated in tumor tissues." (PMID 31807118, 2019). "In agreement, a meta-analysis of pooled B4GALT1 and SCD1 mRNA expression data from TCGA conducted to similar results, thus suggesting a potential co-regulatory activity in tumor progression of SCD1 and B4GALT1 genes." (PMID 31717588, 2019). "To additionally evaluate the prognostic ability of B4GALT1 expression as a prognosticator, we created prognostic models that combine B4GALT1 expression with TNM stage and tumor grade by C-index for comparison of their prognostic reliability." (PMID 29793447, 2018). "The predictors included tumor T stage, ECOG-PS, Fuhrman grade, necrosis and B4GALT1 expression, all of which were independent prognostic indicators for OS." (PMID 27092876, 2016). "To examine if this discovery was separate from well-established prognostic indicators, such as pathological T stage, tumor grade, LVI, and CCI, we conducted Cox proportional hazard analyses (univariate and multivariate) of each of the clinicopathological variables with B4GALT1 expression." (PMID 29793447, 2018). "B4GALT1 expression was significantly connected to tumor grade in the training group but not in the validation group (P = 0.017 and P = 0.950, respectively)." (PMID 29793447, 2018). "B4GALT1 mRNA levels negatively correlated with CD8 + T-cell infiltration, and tumours with higher B4GALT1 mRNA levels had higher tumour immune dysfunction and exclusion (TIDE) scores than those with lower B4GALT1 expression, suggesting the immunosuppressive role of B4GALT1 in LUAD tumorigenesis." (PMID 37303063, 2023). "Moreover, the B4galt1 inhibition and PD-1 blockade combination therapy group showed the most significant reduction in tumour burden compared with the other groups, and neither body weight loss nor other common toxic effects were observed." (PMID 37303063, 2023). "Moreover, we analyzed tumor tissues by an IHC assay and found that RBMS1-depletion induced reduction of PD-L1 and elevated infiltration of CD8+ T cells could be reversed by re-expression of B4GALT1, resulting in increased levels of PD-L1 and Ki67, but decreased infiltration of CD8+ T cells." (PMID 35538152, 2022). "The expression of B4GALT1 and OSMR in tumor was three and four times lower than in normal tissue (NN), respectively (right)." (PMID 19662090, 2009). "To investigate whether this finding was independent of well-known prognostic indicators like tumor T stage, Fuhrman grade, necrosis and ECOG-PS, we performed univariate and multivariate Cox analyses of all the clinicopathological variables with B4GALT1 expression." (PMID 27092876, 2016).
cancer (24 papers, 2009 to 2025). A tumor composed of atypical neoplastic, often pleomorphic cells that invade other tissues. "Several reports have shown that B4GALT1 promotes malignant phenotypes and is associated with poor survival in many cancer types." (PMID 37907465, 2023). "B4GALT1, a key enzyme in N-glycan β-1,4 galactosylation, has been implicated in several cancers." (PMID 40860122, 2025). "Given B4GALT1’s role in various cancers and its potential as a target for therapy, 1105486 serves as the first-in-class selective small-molecule inhibitor in this pathway." (PMID 40860122, 2025). "We evaluated the expression of genes that are most frequently altered in malignant cancers and found that the mRNA and protein levels of B4GALT1 and B4GALT4 were increased in CRC cells." (PMID 39231945, 2024). "The examination of GOLM1 and B4GALT1 gene expression in PAAD cancer was conducted using Gene Expression Profiling Interactive Analysis (GEPIA)." (PMID 38608280, 2024). "A conflicting report by Radhakrishnan however, states upregulation of B4GALT1 can be seen in PCa by TNFα stimulation to increase motility and invasiveness of the disease and multiple reports show upregulation of B4GALT1 increases drug resistance in cancers." (PMID 36937454, 2023). "B4GALT1 has increased expression in several cancers including glioblastoma, breast cancer, and leukaemia, but shows decreased expression in colorectal, endometrial, and metastatic prostate cancers." (PMID 36937454, 2023). "Since the relative abundance of galactosylation and related glycans changes steadily over time, we explored how the B4GALT1 in spleen B cells changes after cancer induction and found that the B4GALT1 in spleen B cells also increased after cancer induction." (PMID 35267641, 2022). "All these results point toward the role of B4GALT1 in the basic pathological process in common with fibrosis and cancer and suggest the key role of this gene in both conditions." (PMID 36499368, 2022). "Subsequently, the elevated B4GALT1 promotes PD-L1 glycosylation and increases PD-L1 protein stability, preventing cancer cells from immune attacks." (PMID 35538152, 2022). "B4GALT1 has been reported before to facilitate cancer cell proliferation, invasiveness, and metastasis in several cancer types." (PMID 31717588, 2019). "The expression alterations of B4GALT1 have been noted in some types of cancer and they are related to cancer cell proliferation, invasiveness, metastasis, and drug resistance." (PMID 29793447, 2018). "Moreover, the migratory activities of these B4GALT1-expressing cancer cells were suppressed by rGal-8, as observed in the CRC cell line experiments." (PMID 39231945, 2024). "The correlation between B4GALT1 expression and malignant behaviors differs across various cancers." (PMID 37907465, 2023). "The opposite role of B4GALT1 could be attributed to the existence of different B4GALT1 protein substrates in different cancer types." (PMID 37907465, 2023). "CKO B4GALT1 reduces serum IgG galactosylation levels and reduces cancer formation." (PMID 35267641, 2022). "Based on the premise of low cancer incidence in female mice, these results again verified that B4GALT1 and serum IgG galactosylation levels in B cells are highly correlated with HCC, although our study revealed the possibility that the incidence of male cancer is higher than that of females." (PMID 35267641, 2022). "In addition, its role in B4GALT1 on HCC formation and its association with HCC-related IgG glycan alteration are further explored by performing cancer induction in CD19-cre+/− B4GALT1flox/flox mice and in B4GALT1-deficient (B4GALT1+/−) mice." (PMID 35267641, 2022). "Among B4GALTs the B4GALT1 is an emerging gene involved in cancer stem cell propagation." (PMID 36499368, 2022).
cancer (continued). "Expression of B4GALT1 was then evaluated, both at the mRNA and protein levels, on lung specimens obtained from lung biopsies of 4 IPF patients, on one IPF-derived human primary cell and on 11 cases of IPF associated with cancer." (PMID 36499368, 2022). "Increased β4GalT1 expression and activity is significantly correlated with differentiation and mobilization of granulocytes and with the metastatic potential of specific cancer cells." (PMID 31953383, 2020). "In 4/5 groups the patients with a more advanced disease showed lower expressions of the B4GALT1 gene, corroborating the hypothesis that the downregulation of the gene may occur more frequently in late phases of cancer progression." (PMID 31635093, 2019). "Consistent with these predictions, a meta-analysis of the TCGA datasets re-computed from raw RNA-seq by XENA project revealed that higher expression of B4GALT1 mRNA is linked with poor survival in many cancers (data not shown)." (PMID 31717588, 2019). "In the analysis of key genes co-expression, we found the four genes (CDC73/CDC123/B4GALT1/CUL2) are most relevant to the expression of key genes and also related to the occurrence of many cancers." (PMID 35111402, 2022). "After analyzing the B4GALT1 mRNA level in spleen B cells and the relative abundance of GP16, we found that there were more male mice with a significantly higher cancer incidence than there were female mice with a lower cancer incidence." (PMID 35267641, 2022). "Network analysis indicated that B4GALT1 upregulation was related to genes belonging to the EMT pathway, known to be involved in both fibrosis and cancer." (PMID 36499368, 2022). "As a result, we found that 3′-phosphoadenosine 5′-phosphosulfate synthase 2 (PAPSS2), γ-tubulin gene 2 (TUBG2), NTRK2, B4GALT1, and OSMR as well as SFRP4 harbored cancer-specific methylation with high frequencies (>30%)." (PMID 19662090, 2009). "In addition, we found that MAN1A1 and MAN2C1 are downregulated in most cancer types, whereas B4GALT1 and B4GALT3–5 are upregulated in most cancer types." (PMID 41093273, 2025). "Studies on B4GALT1 and OSMR have been reported in human cancer." (PMID 19662090, 2009). "Moreover, Western blot analysis indicated that B4GALT1 could be easily detected in HCC cell lines and was expressed in different cancer cell lines at variable levels." (PMID 37907465, 2023). "The role of B4GALT1 in cancer is not surprising and is not new." (PMID 36499368, 2022). "The overexpression of B4GALT1 was observed, both at mRNA and protein levels, in lung biopsies of our four IPF patients and in the IPF-derived human primary cell, in other fibrotic non-lung tissues, and in IPF associated with cancer." (PMID 36499368, 2022). "In addition to integrins, we identified other glycoproteins regulated by B4GALT1, such as neutral amino acid transporter (SLC1A5), insulin receptor (INSR), and growth/differentiation factor 15 (GDF15), which have been reported to modulate cancer malignant phenotypes." (PMID 37907465, 2023).
infection (3 papers, 2020 to 2025). The state of being infected such as from the introduction of a foreign agent such as serum, vaccine, antigenic substance or organism. "Compared to mock-infected cells, AIV infection significantly upregulated the expression of ST3GAL6 and MGAT2 genes at 12-, 24-, 36-, and 48-hours post-infection, and ST3GAL1 gene at 24-, 36-, and 48-hours post-infection, while B4GALT1 expression remained largely unchanged." (PMID 39652582, 2024).
hematologic cancers (2 papers, 2019 to 2020). "In this respect the previous observation in hematologic cancers that B4GALT1 is responsible for drug resistance by regulating the expression of P-gp and MDR- associated protein acquires particular relevance given the known ability of CSCs to be drug resistant." (PMID 31717588, 2019). "The wide variety of TFBS suggests that B4GALT1 contains a super-enhancer region and thus emerges as a previously unrecognized gene that regulates cell identity, disease, and promotes multidrug resistance in hematologic cancers resistance." (PMID 31953383, 2020). "The promoter region of the evolutionarily highly conserved B4GALT1 gene encoding β4GalT1 is rich in enhancer sequences for transcription factors associated with thrombopoiesis, such as E2F1, cell identity regulatory programs, and hematopoietic tumor drug resistance." (PMID 31953383, 2020).